GNA11 (G protein subunit alpha 11)
Diseases named in the same sentence as GNA11 in open-access papers (continued):
Sharing a sentence is not in itself a finding about the gene and the disease.
CNS melanoma (3 papers, 2015 to 2025). "The authors reported 2 cases of children with melanoma of the CNS that presented mutations in the NRAS gene, and highlighted that melanoma of the CNS is associated with mutations in the GNAQ and GNA11 genes, whereas mutations in the NRAS gene are rare in adults." (PMID 26622814, 2015).
colorectal cancer (3 papers, 2018 to 2024). A primary or metastatic malignant neoplasm that affects the colon or rectum. "GNA* (GNAS, GNAQ, or GNA11) aberrations in gastrointestinal excluding appendiceal and colorectal cancer account for 7.3% in all GNA* mutated tumors, and there is a trend toward lower median overall survival in patients with GNA* mutated tumors compared with GNA* wild-type tumors." (PMID 34568004, 2021). "Here, using real gene expression data, we applied CSER to construct a colorectal cancer GRN and successfully identified several key regulatory genes closely related to colorectal cancer (CRC), including ADAMDEC1, CLDN8, and GNA11." (PMID 39371416, 2024).
congenital hemangioma (3 papers, 2020 to 2025). A hemangioma present and fully formed at birth. "In congenital hemangioma, syndromic and non-syndromic capillary malformation mutations have been found on the guanine nucleotide-binding protein subunit alpha-11 (GNA11) or guanine nucleotide-binding protein G(q) subunit alpha (Gαq) (GNAQ) genes." (PMID 37830671, 2023). "Somatic activating mutations in GNAQ and GNA11 have been identified in a subset of congenital hemangiomas." (PMID 33194900, 2020).
hepatocellular carcinoma (3 papers, 2021 to 2023). A malignant tumor that arises from hepatocytes. "Besides mutations, the GNA11 gene promoter was also found to be hypermethylated in hepatocellular carcinoma (HCC) and was proposed as a promising biomarker for diagnosis and targeted therapy." (PMID 37396036, 2023). "Our previous study indicated that GNA11 was involved in the development of hepatocellular carcinoma (HCC) and might be a potential biomarker in HCC detection." (PMID 34568004, 2021).
lung carcinoma (3 papers, 2022 to 2023). "Another research showed that the AUC of an anti-GNA11 autoantibody for distinguishing lung cancer from normal controls was 0.724." (PMID 36835134, 2023). "Autoantibodies to GNA11 were also found in the sera of patients with esophageal squamous cell carcinoma and patients with lung cancer, and may serve as biomarkers for early detection in those two types of cancers." (PMID 36835134, 2023).
melanocytic neoplasm (3 papers, 2014 to 2021). "On the other hand, Q209 and R183 mutations in either GNAQ or GNA11 are rare in melanocytic neoplasms arising in the epithelium, which are more likely to carry mutations in the MAPK pathway components, BRAF, NRAS, and NF1." (PMID 34939927, 2021). "Oncogenic GNAQ and GNA11 mutations are observed at a high frequency in human melanocytic neoplasms in non-epithelial tissues." (PMID 34939927, 2021).
ocular melanoma (3 papers, 2014 to 2023). A melanoma that arises from the structures of the eye or ocular adnexa. "GNA11 aberrations were found to exhibit the strongest association with ocular melanoma and appendiceal cancer across a range of malignancies." (PMID 37396036, 2023). "The genetic profile of CM differs from UM, another subtype of ocular melanoma, in which mutations in GNAQ/GNA11 are frequently described." (PMID 34071371, 2021).
Sturge-Weber syndrome (3 papers, 2024). Sturge-Weber syndrome (SWS) is a rare congenital neurocutaneous disorder characterized by facial capillary malformations and/or cerebral and ocular ipsilateral vascular malformations that result in variable degrees of ocular and neurological anomalies. "Mosaic variants in genes GNAQ or GNA11 lead to a spectrum of vascular and pigmentary diseases including Sturge-Weber syndrome, in which progressive postnatal neurological deterioration led us to seek biologically targeted therapeutics." (PMID 37802293, 2024). "Mosaic mutations in genes GNAQ or GNA11 lead to a spectrum of diseases including Sturge-Weber syndrome and phakomatosis pigmentovascularis with dermal melanocytosis." (PMID 37802294, 2024).
adenoma (2 papers, 2023 to 2024). A neoplasm arising from the epithelium. "Double somatic mutations in CTNNB1 and GNA11/Q have recently been identified in a small subset of aldosterone-producing adenomas (APAs)." (PMID 38505749, 2024). "More recently, overexpression of LHCGR required combined mutations of GNA11 and GNAQ in CTNNB1-mutant aldosterone-producing adenomas presenting in puberty, pregnancy or menopause." (PMID 36926028, 2023).
autosomal dominant hypocalcemia types 1 (2 papers, 2020 to 2022). "Type 1 autosomal dominant hypocalcemia is primarily caused by mutations in the calcium-sensing receptor gene (CASR), whereas mutations in the G protein subunit alpha 11 gene (GNA11) lead to type 2 autosomal dominant hypocalcemia." (PMID 32986719, 2020).
diabetes (2 papers, 2010 to 2021). "Therefore, CaSR could couple to many G proteins within pancreatic tissue, and this may explain why no overt pancreatic phenotypes (e.g. diabetes, variations in blood glucose or insulin levels) have been reported in patients with GNA11 mutations." (PMID 34077389, 2021).
Hypertension (2 papers, 2024). The presence of chronic increased pressure in the systemic arterial system. "Of particular note, one of the 16 cases in Zhou’s study had the same combination of mutations as our case (CTNNB1 p.D32Y and GNA11 p.Q209H) and the patient had no history of hypertension during her past 10 pregnancies." (PMID 38505749, 2024).
lymphatic malformation (2 papers, 2024). Primary lymphedema is caused by anatomic or functional defects in the lymphatic system, resulting in chronic swelling of body parts and lymphatic-system malformation. "We identified somatic variants within 26 of 44 (59%) individuals with slow-flow anomalies (either lymphatic malformation, venous malformation (VM), or mixed lymphatic/venous malformations) within the genes PIK3CA, TEK, GNAQ, BRAF, GNA11, and PIK3R1 with VAFs ranging between 0.7% to 24.8%." (PMID 39669602, 2024).
neurocutaneous melanocytosis (2 papers, 2016 to 2025). Neurocutaneous melanocytosis (NCM) is a rare congenital neurological disorder characterized by abnormal aggregations of nevomelanocytes within the central nervous system (leptomeningeal melanocytosis) associated with large or giant congenital melanocytic nevi (CMN). "Furthermore, like in UMs, in two cases the SF3B1 mutation co-occurred with a GNAQ or GNA11 mutation, while in a third case (with neurocutaneous melanocytosis) an NRAS mutation was present." (PMID 26769193, 2016). "CNS melanocytic tumors, including neurocutaneous melanosis and nevus of Ota, frequently exhibit mutations in the GNAQ and GNA11 genes, as compared to BRAF, NRAS, HRAS, and KIT mutations seen in non-CNS originating melanocytic lesions." (PMID 41303082, 2025).
non-small cell lung carcinoma (2 papers, 2012 to 2020). A group of at least three distinct histological types of lung cancer, including non-small cell squamous cell carcinoma, adenocarcinoma, and large cell carcinoma.
parathyroid adenoma (2 papers, 2019 to 2023). "However, in contrast to cases with FHH due to pathogenic variants in CASR, AP2S1, or GNA11, surgery may cure the disease (Case 3) unless hyperplastic glands or other parathyroid adenomas are missed during the first surgery in cases of MGH (Case 2)." (PMID 38130397, 2023).
phakomatosis pigmentovascularis (2 papers, 2016 to 2024). "Here, we discover that extensive dermal melanocytosis and phakomatosis pigmentovascularis are associated with activating mutations in GNA11 and GNAQ, genes that encode Gα subunits of heterotrimeric G proteins." (PMID 26778290, 2016).
thyroid cancer (2 papers, 2013 to 2018). "The sequencing results showed no mutations in and around the hot spot of codons 209 and 183 in the GNA11 gene in 12 thyroid cancer cell lines and 46 thyroid cancer samples (including 26 FTC and 20 ATC samples)." (PMID 24137342, 2013). "The present study reports for the first time the mutational status of the GNA11, MMP27, FGD1, TRRAP and GRM3 genes in thyroid cancer." (PMID 24137342, 2013). "The mutation status in the GNA11, MMP27, FGD1, TRRAP and GRM3 genes has not been studied in thyroid cancer." (PMID 24137342, 2013). "In conclusion, the present findings suggested that genetic alterations in the GNA11, MMP27, FGD1, TRRAP and GRM3 genes may not be significant in the tumorigenesis of thyroid cancer." (PMID 24137342, 2013).
uveal tumors (2 papers, 2017 to 2024). "In seven cases BAP1mut non-uveal tumors were identified harboring activating GNAQ or GNA11 mutations." (PMID 38903495, 2024). "The sample contained a GNA11 mutation, indicative of metastasis from the uveal tumour." (PMID 28228113, 2017).
22q11.2 deletion syndrome (1 paper, 2023). 22q11.2 deletion syndrome (DS) is a chromosomal anomaly which causes a congenital malformation disorder whose common features include cardiac defects, palatal anomalies, facial dysmorphism, developmental delay and immune deficiency. "Although 22q11.2 deletion syndrome and chromosomal abnormalities were ruled out in this case, a genetic etiology could not be ruled out as the patient was not evaluated for other genetic abnormalities such as NEBL, TBCE, FAM111A, CASR, and GNA11 mutations." (PMID 36865979, 2023).
adrenal tumors (1 paper, 2022). "Somatic mutations that constitutively activate WNT/β-catenin (CTNNB1), G-protein (GNAS, GNAQ, GNA11), and cAMP/protein kinase A (PKA) (GNAS, PRKACA) signaling can drive unrestrained cell proliferation and survival in diverse tumors, including adrenal tumors." (PMID 36004349, 2022).
Alzheimer disease (1 paper, 2018). A progressive, neurodegenerative disease characterized by loss of function and death of nerve cells in several areas of the brain leading to loss of cognitive function such as memory and language. "PANTHER pathways analysis of differentially expressed proteins revealed overrepresentation of Wnt signaling pathway (CDH1, CSNK2A2, GNA11, CTBP2, CDH17, SMARCE1, p-value 0.02), followed by Alzheimer disease-presenilin pathway (MMP8, MMP9, MLLT4, CDH1, P-value 0.04)." (PMID 29515771, 2018).
anaplastic thyroid cancer (1 paper, 2013). "No GNA11 mutations were identified in the papillary thyroid cancer (PTC), follicular thyroid cancer (FTC) and anaplastic thyroid cancer (ATC) samples." (PMID 24137342, 2013).
angiosarcoma (1 paper, 2021). A malignant tumor arising from the endothelial cells of the blood vessels. "In our cohort of angiosarcomas no alterations in GNA14 or GNA11 were identified." (PMID 34040639, 2021).
basal cell carcinoma (1 paper, 2021). A carcinoma involving the basal cells.
benign vascular tumor (1 paper, 2021). "Frequent activating hotspot mutations in GNA genes, including GNA14 Q205, GNA11 and GNAQ Q209 were identified in 16 of 64 benign vascular tumors (25%)." (PMID 34040639, 2021).
bladder cancer (1 paper, 2020). "Despite these reports, the only clinical trial that utilizes MEK inhibition in bladder cancer is the ongoing MATCH screening trial in advanced solid tumors (NCT02465060), using mutation status of BRAF, GNA11, and NF1 to identify potential responders to the MEK inhibitor, Trametinib." (PMID 33216841, 2020).
cervical cancer (1 paper, 2023). A primary or metastatic malignant neoplasm involving the cervix. "Tian et al30 identified that the cervical cancer patients with five notable nonsynonymous mutant genes (PIK3CA, BRAF, GNA11, FBXW7, and CDH1) metastatic relapse significantly mutated mutations had significantly poor DFS and OS." (PMID 35762423, 2023).
choroidal hemangioma (1 paper, 2019). "Here, we report the results of GNAQ/GNA11 mutation analysis in samples from circumscribed choroidal hemangioma." (PMID 31336681, 2019). "Deep amplicon sequencing (Illumina MiSeq, San Diego, CA, USA) of positions R183 and Q209 of GNAQ and GNA11 in tissue samples from 33 patients with histologically diagnosed circumscribed choroidal hemangioma." (PMID 31336681, 2019).
choroidal melanoma (1 paper, 2015). Malignant tumor of melanocytes of the choroid. "In order to investigate GNAQ and GNA11 mutation, according to anatomic location, UM were grouped in choroidal melanoma, ciliochoroidal melanoma and iridociliary melanoma." (PMID 26368812, 2015).
depression (1 paper, 2022). "Consistent with the PPI network, Asmt knockout may play an important role through Mtnr1b/Gna11/Plcb2/Bdnf in depression." (PMID 35771226, 2022).
endometrial cancer (1 paper, 2015). Primary or metastatic malignant neoplasm involving the endometrium (mucous membrane that lines the endometrial cavity).
esophageal adenocarcinoma (1 paper, 2021). A malignant tumor with glandular differentiation arising predominantly from Barrett mucosa in the lower third of the esophagus. "GNA11 gene was frequently mutated in the conventional esophageal adenocarcinoma, and the mutation was related to critical cellular pathways including PI3K, RAS, and MAPK, which suggested that GNA11 mutation might be tightly linked to the occurrence of EC." (PMID 34568004, 2021).
esophageal squamous cell carcinoma (1 paper, 2021). Esophageal squamous cell carcinoma (ESCC) is a type of esophageal carcinoma (EC) that can affect any part of the esophagus, but is usually located in the upper or middle third. "The study aims to explore the diagnostic value of anti-GNA11 autoantibody in esophageal squamous cell carcinoma (ESCC) from multiple levels." (PMID 34568004, 2021).
Hypermagnesemia (1 paper, 2017). An abnormally increased magnesium concentration in the blood. "Gna11+/195G mice additionally had normal plasma magnesium concentrations, which is consistent with one reported FHH2 proband but which contrasts with the hypermagnesemia reported in a multigenerational FHH2 kindred." (PMID 29046478, 2017).
hypocalciuric hypercalcemia type II (1 paper, 2020). "Similarly, mutations in the GNA11 locus have been found associated with hypocalciuric hypercalcemia type II (HHC2), hypocalcemia dominant 2 (HYPOC2), and uveal melanoma conditions." (PMID 32066657, 2020).
hypophosphatemia (1 paper, 2017). Lower than normal levels of phosphates in the circulating blood. "In addition, female Gna11195G/195G mice, but not the Gna11 mutant males, had significant hypophosphatemia, with a significant reduction in the tubular maximum reabsorption of phosphate and a raised alkaline phosphatase activity compared with female Gna11+/+ mice." (PMID 29046478, 2017).
mastitis (1 paper, 2023). Inflammation of breast tissue during lactation or postpartum due to an obstructed duct or infection. "One of the essential hub genes downregulated in mastitis animals was GNA11, which encodes for a type of guanine nucleotide-binding protein (G-protein) functioning as a modulator or transducer in the transmembrane signaling systems." (PMID 37403140, 2023).
melanocytic nevus (1 paper, 2016). A neoplasm composed of melanocytes that usually appears as a dark spot on the skin. "Instead of GNAQ or GNA11 mutations, these patients frequently demonstrate identical NRAS mutations in both the congenital melanocytic nevus and in the LMN." (PMID 26769193, 2016).
neurocutaneous disorder (1 paper, 2025). "Sturge–Weber Syndrome (SWS) is a rare, sporadic neurocutaneous disorder affecting the skin, brain, and eyes, due to somatic activating mutations in GNAQ or, less commonly, GNA11 gene." (PMID 39819452, 2025).
neurofibroma (1 paper, 2025). An intraneural or extraneural neoplasm arising from nerve tissues and neural sheaths. "Given the strong similarity between neurofibromas and mouse sparse pigment tumors, combined with the fact that GNAQQ209L alone was able to stimulate their formation, we investigated the cBioPortal for Cancer Genomics database to search for mutations in GNAQ or GNA11." (PMID 39804140, 2025).
nevus (1 paper, 2021). Nevus (or naevus, plural nevi or naevi, from nævus, Latin for "birthmark") is the medical term for sharply circumscribed[1] and chronic lesions of the skin or mucosa. "In nevus 12B, the only one being GNAQ and GNA11 wild-type, we now identified this CYSLTR2 mutation, while only CYSLTR2 wild-type alleles were detected in other nevi." (PMID 33588787, 2021).
parathyroid tumors (1 paper, 2021). "In molecular genetic analyses of sporadic parathyroid tumors, somatic loss-of-function mutation in the genes encoding GNA11 and AP2S1 have thus far not been described." (PMID 33716975, 2021).
primary aldosteronism (1 paper, 2025). An endocrine disorder characterized by excessive production of aldosterone by the adrenal glands. "However, a case report of a Japanese female patient with the same double mutations (GNA11/Q and CTNNB1) presented with primary aldosteronism and hypokalaemia despite having a normal menstrual cycle and in the absence of pregnancy-induced hypertension." (PMID 40725432, 2025).
renal carcinoma (1 paper, 2022). A carcinoma arising from the epithelium of the renal parenchyma or the renal pelvis. "Immunohistochemical staining results of the bioinformatics analysis showed that the protein levels of GNA11 and THRAP3 were significantly decreased in renal cancer tissues, and the protein levels of CSNK1E did not change significantly." (PMID 35877357, 2022).
sarcopenia (1 paper, 2024). Progressive decline in muscle mass due to aging which results in decreased functional capacity of muscles. "Inactivation of Gna12-Gna13 or Rhoa but not of Gnaq-Gna11 completely abrogated MuSC quiescence, which depleted the MuSC pool and was associated with accelerated sarcopenia during aging." (PMID 39009565, 2024).